TNF (tumor necrosis factor)
Diseases named in the same sentence as TNF in open-access papers (continued):
Sharing a sentence is not in itself a finding about the gene and the disease.
Sepsis (continued). "A very recent study demonstrated that basophil-deficient mice exhibited reduced bacterial clearance and increased mortality in a cecal ligation and puncture model of sepsis and such effect was due to reduced basophil-derived TNF production." (PMID 33546401, 2021). "It has been reported that serum cytokines such as IL-1β, IL-6, IL-8, IL-10, IL-12, IL-17A, IL-18, interferon gamma (IFN-γ), and TNF-α are elevated in sepsis, but some of these cytokines are also elevated in FMF patients." (PMID 34654467, 2021). "NEAT1 showed a good predictive value for increased sepsis risk.NEAT1 expression was positively associated with disease severity, CRP, PCT, TNF-α, and IL-1β, 28-day deaths." (PMID 34956235, 2021). "MicroRNA (miRNA) profiling and reverse transcription and quantitative polymerase chain reaction (RT-qPCR) revealed a sepsis-induced exosomal increase in multiple miRNAs, which putatively target TNF-α and IL-17A." (PMID 33182773, 2020). "Several studies have shown that glycine has an anti-inflammatory role, not just in the oral gingiva, but also in sepsis by reducing tumor necrosis factor alpha (TNF-α)." (PMID 33552029, 2020). "Similar to sepsis, the processes of TNF-α upregulation and its subsequent binding to TNFR1 also play crucial roles in immune-mediated diseases, e.g., autoimmune disease." (PMID 33003495, 2020). "Other SNPs located in the promoter of the gene (-238G/A, -376G/A) seem to have a functional importance in TNF-α response and subsequently in its ability to augment its deleterious effects and eventually affect morbidity and mortality in sepsis." (PMID 32171247, 2020). "Gas6‐/‐ mice were injected with TNF‐α to investigate sepsis and transplantation‐induced organ destruction, considering the organismic influence brought on by gas6 knockout, it is hard to attribute this effect to endothelial cells alone." (PMID 32462812, 2020). "For TNF-α mRNA, sepsis tended to induce similar effects, but the difference was significant only for the ALA and EPA groups (+169 and +103%, respectively)." (PMID 32365668, 2020). "Reportedly, treatment with IL-34 also assisted to protect mice against polymicrobial sepsis by inducing the expression of cytokines (IL-6, TNFα) and chemokines (CXCL1, CCL2)." (PMID 32231137, 2020). "Doxycycline ameliorated pulmonary inflammation in a murine polymicrobial sepsis model by decreasing levels of IL-1β, IL-6 and TNFα in plasma and lungs." (PMID 33142770, 2020). "It was found that proinflammatory cytokines, including IL-1β, IL-6, and TNF-α, substantially decreased after EVs were applied to LPS-stimulated macrophages and mice, and thus, LPS induced M1 polarization was inhibited and sepsis was strongly alleviated." (PMID 32719678, 2020). "Sepsis scores were thus found to be in strong linear correlation with the concentrations of IL-6, IFNγ, and TNFα and again, higher sepsis scores in mice with pre-existing CIA correlated with elevated levels of these cytokines." (PMID 33117382, 2020). "Both TNF-α and IL-6 are the central mediators of sepsis, which is uncontrolled inflammatory response which can result in multi-organ failure and even demise." (PMID 33028307, 2020). "LPS is a cytotoxic agent that can induce inflammatory response and increase the expressions of inflammatory factors TNFα, IL-6, IL-8 and IL-1β, leading to sepsis." (PMID 32484206, 2020). "These authors also noted significant differences in TNF-α plasma levels - increased in sepsis and septic shock patients compared to SIRS and healthy controls, deducing an increased production of the cytokine in patients with -238G/A SNP." (PMID 32171247, 2020). "CLP induced increases in extracellular histone levels, with this elevation peaking in the late phase of sepsis followed by the peak in tumor necrosis factor (TNF)-α level." (PMID 31971961, 2020). "TNFα plays a pivotal role in sepsis-mediated organ dysfunction and induces cerebral edema via TNF receptor 1-mediated pathways in a mouse model." (PMID 32050431, 2020).
Sepsis (continued). "TNF-α can initiate inflammatory edema in experimental settings and sepsis and general inflammatory states affect the endothelial surfaces throughout the body." (PMID 33108383, 2020). "In the sepsis+MLD group, the mRNA expression of TNF-α, IL-1β, and IL-6 in the lung was significantly decreased, compared with the sepsis group (p < 0.05)." (PMID 33145344, 2020). "Functionally, Tim-3 is shed from monocytes induced by LPS to produce sTim-3, which plays an inhibitory role in sepsis as well as expression of TNF-α and IL-1218." (PMID 32714569, 2020). "Through activation of the TNF and mTORC1 pathways, sepsis impairs the physiological anabolic response of muscles to contraction, thereby slowing down recovery from atrophy." (PMID 32176432, 2020). "T cells harvested from the spleen of patients who died of sepsis have only a low capacity to produce IFNγ and TNF, suggesting a state of T-cell exhaustion." (PMID 33679715, 2020). "An increased release of catecholamines occurs in the initial stage as well as in the acute and late stage of sepsis and is enhanced by the released pro-inflammatory cytokines (Interleukin (IL)-6, Tumor Necrosis Factor (TNF)-α)." (PMID 32708472, 2020). "This ‘cholinergic anti-inflammatory pathway’ of the vagus nerve has been acknowledged for many years, in particular at the level of sepsis-related cytokines Tumor Necrosis Factor (TNF), Interleukin (IL)-1, and High Mobility Group Box 1 (HMBG1)." (PMID 33123616, 2020). "Further inflammatory mediators involved in sepsis pathogenesis are the pro-inflammatory cytokines tumor necrosis factor-α (TNF-α), interferon-γ (IFN-γ), and the interleukins IL-1β and IL-6." (PMID 32948040, 2020). "Sepsis rats generated by cecal ligation puncture had significantly reduced TNF-α and IL-6 levels after XBJ treatment." (PMID 32082396, 2020). "Our results showed that females expressed higher IL-6 and TNFα than males in sepsis, and trained immunity exacerbated this trend." (PMID 32793229, 2020). "Under septic conditions, pro‐inflammatory cytokines, such as TNFα and IL‐6, evoke cytokine storms, which are responsible for tissue damage during sepsis." (PMID 32394600, 2020). "For this purpose, we used antagomir-21 to inhibit miR-21 expression in murine sepsis model and detected the levels of proinflammatory cytokines (TNF-α, IL-1β, and IL-6), liver injury markers (AST, ALT), and PPARα expression." (PMID 33424957, 2020). "Sepsis is a lethal condition, accompanied by acute inflammatory responses, with the release of multiple inflammatory factors such as TNF-α and IL-6." (PMID 32188465, 2020). "Plasma TNF-α levels were significantly higher in the septic shock (SS) patient subgroup (median 57.3 pg/mL; range: 10.21–207.5 pg/mL) compared to the sepsis (S) subgroup (median 42.9 pg/mL; range: 10.2–207.1 pg/mL; p = 0.0007)." (PMID 32171247, 2020). "Infectious complications and sepsis enhance the proinflammatory cytokine cascade, including TNF-α, IL-1, IL-6, and IL-8." (PMID 33643891, 2020). "Binding of LPS to CD14 leads to the activation of immune cells and excessive production of TNF-α, playing a critical role in sepsis." (PMID 32230846, 2020). "Many therapeutics attempt treatment of sepsis via targeting at tumor necrosis factor alpha (TNF-α) or interleukin (IL)-1." (PMID 33603756, 2020). "Using this model, the authors were able to replicate clinical trial data showing TNF-α neutralization was ineffective in their dirty mice (just like in human sepsis patients), even though it was an effective therapy for SPF mice." (PMID 32733454, 2020). "In mammals, local production of tumor necrosis factor α (TNFα) inhibits growth hormone (GH)-induced IGF-I expression at tissue level and contributes to GH resistance caused by sepsis/endotoxemia and inflammation." (PMID 32082258, 2020).
Sepsis (continued). "GTS-21, a synthetic selective stimulant of α7nAchR, has been shown to reduce myocardial injury via modulating inflammation (decreases in IL-6, IL-1β, TNF-α and activation of NF-κB P65) and apoptosis in LPS-induced sepsis in mice." (PMID 32194424, 2020). "Sepsis is a systemic inflammatory reaction syndrome, accompanied by acute inflammatory responses, with the release of multiple inflammatory factors such as TNF-α and IL-6." (PMID 32188465, 2020). "The level of TNF-α in the kidney tissue was found to be significantly higher in the sepsis + cefazolin group than thatin the control group (p < 0.05)." (PMID 32348434, 2020). "In conclusion, our results found that mice with sepsis showed an obvious intestinal barrier dysfunction with an increase of TNF-α, IL-6, and IL-10 in the ileum." (PMID 33376482, 2020). "This is further reinforced by the fact that the M1 cytokines, IL1, IL‐6 and TNF are consistently increased in the hippocampus late after sepsis, and IL‐10 has some peaks during sepsis evolution and CCL‐22 is not increased at all." (PMID 31654493, 2020). "When survivors of the two groups were compared, the levels of serum IL-2R, IL-6, IL-8, and TNF-α were lower in SARS-CoV-2 sepsis survivors." (PMID 33329592, 2020). "The results obtained showed that the rats in the untreated sepsis group showed significantly elevated levels of pro-inflammatory cytokines (IL-1α, IL-2, TNF-α, IL-6, IFN-γ, IL-1β) in plasma." (PMID 32076015, 2020). "Brain tissue reached its peak tissue TNF concentration (mean 950 pg/mg protein) after 5.5 h of sepsis duration." (PMID 33072121, 2020). "This study was therefore performed to investigate the interactions among THRIL, miR-19a and TNF-α in sepsis." (PMID 32944003, 2020). "When comparing the Sepsis-G group to the sham and Sepsis-C groups at 72 h, only the Sepsis-C group demonstrated significant increases in TNF-α and IL-6 expressions." (PMID 32295272, 2020). "Considering all these evidence, our study supports the contention that sepsis-enhanced functional miRNAs in IEC EVs possess the ability to regulate TNF-α and IL-17A expression in the gut." (PMID 33182773, 2020). "We investigated the role of inflammatory mediators (TNFα and serum from sepsis patients) in a human system based on the function of human brain endothelial cells (hCMEC/D3)." (PMID 32050431, 2020). "In the ileal tissues of healthy mice, sepsis EVs (S-EVs) downregulated messages of the pro-inflammatory cytokines including TNF-α, IL-1β, IL-6, IL-17A, and IL-22." (PMID 33182773, 2020). "We examined four relevant sepsis markers to assess host immune response phenotype: IL-10, TNFα, HLA-DR, and PD-L1." (PMID 32899240, 2020). "Xu et al40,41 established that intravenous injection of histones into mice caused death with higher levels of TNF-α, and IL-6, whereas anti-histone antibodies reduced mortality in lipopolysaccharide, TNF-α, and puncture models of sepsis." (PMID 32217943, 2020). "Whereas elevation of TNF-α occurs for a short period of time in the initial phase of sepsis, the increased levels of IL-6 occur for longer periods and are associated with increased mortality in septic patients." (PMID 33382782, 2020). "We also found that Mr1-/- mice had lower levels of tissue cytokines (IFN-γ, TNF-α, IL-17, GM-CSF) than that in WT mice following induction of sepsis." (PMID 33164745, 2020). "In a retrospective study with 104 patients with sepsis, it has been demonstrated that the combination of PCT, MRproADM, and TNFα had the best performance in early detection of sepsis compared with single biomarkers." (PMID 32831638, 2020). "Plasma IL-6 and TNF-α levels were markedly high in the patient with sepsis, as compared to those in the other cardiogenic post-CA patients." (PMID 33041520, 2020). "TNFα, together with other proinflammatory cytokines (e.g., IL-1β and IL-6), can also act as local mediators for GH resistance induced by sepsis/endotoxemia or chronic inflammation." (PMID 32082258, 2020).
Sepsis (continued). "Following the observation that S-EVs downregulate messaging of TNF-α and IL-17A in the inflamed gut, we attempted to confirm the sepsis-increased expression of several miRNAs predicted to target these genes." (PMID 33182773, 2020). "For example, circ-4099 is induced by inflammatory mediators, such as TNF-α and circRNA_0038644, and has been demonstrated to regulate the expression of NF-κB in sepsis, while IL-6 is regulated by circ_007893." (PMID 32630422, 2020). "The hyper-inflammatory phase presents with dramatic increases of various potent cytokines (called a cytokine storm) including TNF-α and IL-6 in patients with sepsis, and in in vivo mice and human studies." (PMID 33382782, 2020). "A gradual increase of TNF-α plasmatic levels in sepsis was registered, with maximal values in septic shock; this was in agreement with previous studies and supports the prognostic biomarker role generally conferred to this cytokine." (PMID 32171247, 2020). "Several therapeutic strategies for sepsis aim to modulate inflammatory responses such as low-dose glucocorticoids, C-reactive protein inhibitors, TNF-α and IL-1β receptor antagonists, recombinant IL-17, and PD-1 immunotherapy, etc.." (PMID 32153412, 2020). "TNF-α is an especially important cytokine in sepsis and other inflammatory conditions and promotes changings in various metabolic pathways." (PMID 32549262, 2020). "The meta-analyses of TNF-α and IL-6 protein levels after two-challenges show similarities to the clinical sepsis samples." (PMID 33382782, 2020). "When ONB/MPA treatment was employed in murine models of LPS- and CLP-induced sepsis, we observed significant downregulation of growth factors and cytokines (i.e., IL-2, IL-6, and TNF-α)." (PMID 32226527, 2020). "We observed that IL-6 and TNF-α were induced in sepsis mouse models and MEG3 was able to restrain their protein levels." (PMID 32410866, 2020). "The researchers also observed that the levels of IL-1β, IL-6, IL-10, MCP-1, and TNF-α were significantly increased in septic shock as compared with severe sepsis." (PMID 32153410, 2020). "Using a TargetScan bioinfomatics analysis that concentrated on miRNAs upregulated in the intestinal epithelial EVs during sepsis, we examined those miRNAs predicted to target TNF-α, and IL-17A." (PMID 33182773, 2020). "The expression levels of TNF-α, IL-1β, and IL-6 mRNA in the intestine, liver, and lung of the rats in the sepsis group increased significantly, compared with the control and sham surgery groups." (PMID 33145344, 2020). "Patients with sepsis typically have elevated blood levels of endotoxins and cytokines [e.g., interleukin 6 (IL-6), IL-8, IL-10, and tumor necrosis factor alpha(TNF-α)]." (PMID 32144519, 2020). "Nanjo Y. has suggested that the use of colistin sulfate (subcutaneously injected at 1.0 mg per mouse) can reduce the levels of TNF-α, IL-6 and IL-1β in LPS-induced sepsis mouse model and lead to decreased toxicity." (PMID 33551807, 2020). "To further confirm that MAIT cell effector function is impaired during experimental sepsis, we evaluated IFNγ, TNFα, IL-17a, GM-CSF, and IL-10 protein expression in MAIT cells of lung tissue using flow cytometry." (PMID 33164745, 2020). "Monocytes/macrophages are supposed to be potent producers of cytokines such as TNF-α in response to innate immune activation as in sepsis." (PMID 32670276, 2020). "In both sepsis and rheumatoid arthritis, the central role of TNF in dysregulation of the immune system leading to hyperinflammation were assumed to be the essence of the pathology." (PMID 33679715, 2020). "Sepsis induction resulted in analogous increases in TNF-α and IFN-γ with increases of 38.7-fold and 22.4-fold, in vehicle-treated septic pups compared to sham pups, respectively." (PMID 33276725, 2020).
Sepsis (continued). "Stimulation with LPS leads to increased secretion of pro-inflammatory cytokines, including IL-6, TNF-α, and IL-1β in the bloodstream, which are resulted from exacerbation of inflammation in patients with sepsis." (PMID 32079307, 2020). "Peritonitis-induced sepsis resulted in gradually increased plasma levels of TNF-α and IL-6, providing evidence of a progressive systemic inflammatory response." (PMID 32117276, 2020). "One of the signaling pathways known to contribute to sepsis-induced BBB dysfunction is triggered by binding of systemic TNFα to the neurovasculature leading to induction of cyto-/chemokine synthesis that causes BBB disruption." (PMID 32050431, 2020). "In our results, pulmonary H&E showed typical inflammatory infiltration in sepsis-associated ALI, and decreased plasma IL-6/TNF-α through MSCs treatment, effectively alleviated inflammatory infiltration, and reduced bleeding and edema." (PMID 32894198, 2020). "Here, we investigated the ability of intestinal epithelial EVs in sepsis to suppress TNF-α, and IL-17A based on the assumption that such a capability would primarily be mediated by exosomal miRNAs." (PMID 33182773, 2020). "As an early signaling activated in sepsis, NF-κB activates the transcription of a series of proinflammatory cytokines to activate cytokine storm in septic shock, including TNF-α, IL-1β, and IL-12." (PMID 33986658, 2020). "The APOE mRNA and protein levels in septic patients were significantly lower than those of the healthy controls (p = 0.024 and p < 0.001, respectively), while the levels of TNF-α, IL-6, and IL-1β were elevated in sepsis patients." (PMID 32978453, 2020). "Anti-inflammatory GR signaling is crucial for survival in several animal models of sepsis and related to the suppression of TNFα-induced inflammation." (PMID 32477273, 2020). "In sepsis, overexpression of TNF-α increases the level of NO by inducing the production of inducible nitric oxide synthase (iNOS), which leads to apoptosis of myocardial cells and heart failure." (PMID 32908632, 2020). "The jejunal tissue structure and serum levels of TNF-α and IL-1β were assessed to confirm sepsis induction." (PMID 33200654, 2020). "After knockdown ofmiR-451a, the increased levels of IL-1β, IL-6 and TNF-α were reduced significantly(all P < 0.01), indicating that the inhibition of miR-451a in sepsis led to suppressedinflammation." (PMID 33211058, 2020). "Pro-inflammatory cytokines IL-6 and TNF-α play essential roles in the onset and progression of sepsis, and their over-expression was seen as an early signal suppressing myocardial contraction and the major cause of progressive systolic dysfunction." (PMID 32423469, 2020). "In a human system, we investigated the role of inflammatory mediators (TNFα and serum obtained from sepsis patients) on human brain endothelial cell (hCMEC/D3) function." (PMID 32050431, 2020). "The induction of miR-199a in AMs during sepsis increases the release of pro-inflammatory cytokines (IL-1β, IL-6, and TNF-α), the MPO activity, ALI, and the high levels of CASP3, Bax and lowers the Bcl-2 levels." (PMID 32849610, 2020). "In conclusion, our current results reinforce the idea of the importance of a synchronized circadian clock for septic shock survival and the importance of TNF-α signaling in the daily response to sepsis." (PMID 32226779, 2020). "Elevated concentrations of TNF-α and IL-1β are found in the serum of septic patients and are responsible for sepsis-related cardiac depression." (PMID 32908632, 2020). "Studies by Taniguchi and coworkers 28 and Qiao and coworkers 29 demonstrated that dexmedetomidine reduces the concentrations of TNF-α and IL-6, and ameliorates mortality in rats with endotoxin or cecal ligation and intestinal puncture-induced sepsis." (PMID 33029092, 2020). "It is well studied that both IL-6 and TNF-α are the primary mediators of local inflammation and sepsis." (PMID 32079307, 2020).